CRP (C-reactive protein)
Diseases named in the same sentence as CRP in open-access papers (continued):
Sharing a sentence is not in itself a finding about the gene and the disease.
myocardial infarction (continued). "Elevated levels of CRP have been shown to independently correlate with increased CVD risk; a previous study has shown that elevated CRP was associated with an up to threefold increase in the risk of a heart attack." (PMID 27704313, 2016). "Different inflammatory markers such as C-reactive protein (CRP) or pro-inflammatory cytokines such as interleukin-6 or interleukin-1 have been shown to be elevated in patients with myocardial infarction or unstable angina, reflecting low-grade inflammatory status in the vascular bed." (PMID 26340022, 2015). "Similarly, level of proinflammatory markers (hs-CRP, IL-6, and ICAM-1) and pregnancy associated plasma protein-A (PAPP-A) in serum also clearly display myocardial infarction (MI)." (PMID 25949827, 2015). "To disentangle the association of IL6R with inflammation and risk of CHD, we analyzed the association of IL6R haplotypes with circulating levels of inflammatory biomarkers [CRP, fibrinogen, sIL6R, IL6, interleukin 8 (IL8) and TNF-α] and with the risk of myocardial infarction (MI) and CHD." (PMID 25781951, 2015). "Elevated CRP plasma levels predict cardiovascular events among apparently healthy men and women, patients with stable and unstable angina, and patients with a previous history of myocardial infarction." (PMID 25490200, 2014). "During myocardial infarction, the necrotic part of the myocardium will be removed by CRP." (PMID 24948846, 2014). "Following myocardial infarction, an increase in CRP levels is also observed." (PMID 24808639, 2014). "In addition, in humans, PTX3 plasma levels increase during vascular atherosclerosis, inflammation, or damage especially after myocardial infarction and reach the peak much earlier compared to CRP." (PMID 23690668, 2013). "In 1943, Lofstrom reported that patients with myocardial infarction also presented the “non-specific capsular swelling in pneumococci,” later associated with the presence of the “C-reactive protein”." (PMID 23819098, 2013). "Interestingly, preconditioning was found to inhibit postischaemic CRP increases in a rat model of acute myocardial infarction." (PMID 23936799, 2013). "C-reactive protein (CRP), a systemic marker of chronic inflammation, is an acute phase reactant protein that increases during the host response to tissue injury, including infection, trauma, myocardial infarction, surgery, and cancer." (PMID 22912790, 2012). "Acute myocardial infarction (MI) is associated with a systemic inflammatory response with augmented production of nonspecific plasma acute-phase proteins, including C-reactive protein (CRP)." (PMID 22973074, 2012). "The primary purpose of this study was to evaluate the impact of measured peak platelet aggregation, high residual platelet reactivity, defined from PFA-100 closure times, and measured peak CRP, respectively, on the occurrence of cardiovascular events after an acute myocardial infarction." (PMID 19583836, 2009). "Patients who developed systolic dysfunction had lower systolic and diastolic blood pressure at entry, higher entry levels of troponin I, glucose, uric acid, WBC count and serum CRP, lower creatinine clearance as well as higher prevalence of myocardial infarction as a discharge diagnosis." (PMID 19503842, 2009). "Raised levels of C- reactive proteins (CRP) amongst periodontal patients and those with acute myocardial infarction has been reported, independent of other risk factors." (PMID 19088876, 2008). "Of note, rat CRP does not activate rat complement, nor cause these deleterious effects in the rat myocardial infarction model." (PMID 19690638, 2007). "Moreover, patients with fever, major trauma or infections, and myocardial infarction within the preceding 14 days were excluded from the study because of the simultaneous measurement of CRP and the probable influence of these conditions on CRP levels." (PMID 18092110, 2007).
myocardial infarction (continued). "In CANTOS (Canakinumab Anti-inflammatory Thrombosis Outcomes Study), an IL-1β monoclonal antibody canakinumab was investigated in post-myocardial infarction (MI) patients with elevated high-sensitivity CRP (hsCRP)." (PMID 40528106, 2025). "In myocardial infarction (MI), cfDNA’s early peak could complement troponin, while CRP’s delayed rise may guide post-MI anti-inflammatory therapy (e.g., colchicine in patients with high CRP)." (PMID 40282303, 2025). "In addition, salivary C-reactive protein concentration in combination with an electrocardiogram predicted acute myocardial infarction, reinforcing the idea that salivary markers are effective for an early detection of potential alterations in the cardiovascular health." (PMID 38304464, 2024). "A recent study has indicated that employing interleukin-1β inhibition in individuals with a prior myocardial infarction and a high-sensitivity C-reactive protein level ≥ 2 mg/L may lead to a reduction in cardiovascular adverse events without lowering blood pressure." (PMID 38566082, 2024). "However, studies exploring the role of mCRP in other diseases including myocardial infarction and peripheral arterial disease highlighted that mCRP can circulate by binding to cellular microparticles and leukocytes, which aid the conversion of CRP into mCRP." (PMID 36776896, 2023). "For example, the Canakinumab Anti-Inflammatory Thrombosis Outcomes Study investigated whether treatment with canakinumab, a monoclonal antibody that specifically neutralises IL-1b, would benefit people with CRP > 2.0 mg/L and a history of myocardial infarction." (PMID 37953258, 2023). "Moreover, the fact that injury in myocardial infarction has been mitigated by blocking CRP synthesis hints at the plausibility of such a cascade and causative role that CRP could have in the time-delayed cellular damage." (PMID 37360331, 2023). "Research suggests that CRP values between 1 and 5 mg/dL may indicate chronic inflammatory processes, malignant diseases, or rheumatoid diseases, as well as local-tissue necrosis (e.g., myocardial infarction)." (PMID 37107100, 2023). "No attenuation of the results was identified (model C plus log C reactive protein: hazard ratio for cardiovascular disease 1.39 (95% confidence interval 1.21 to 1.60), P<0.001; ischaemic heart disease 1.49 (1.28 to 1.74), P<0.001; and myocardial infarction 1.60 (1.25 to 2.05), P<0.001)." (PMID 36936262, 2023). "A 72-year-old man developed fever and chest pain, accompanied by an increase in C-reactive protein, four days after successful emergency catheter intervention for an acute wide anterior myocardial infarction (MI)." (PMID 35971359, 2022). "In addition, polymorphisms, haplotypes and variability in plasma levels of C-reactive protein, fibrinogen, IL-6 may have altered the pro-inflammatory response of air pollution in myocardial infarction patients." (PMID 35354890, 2022). "In addition, we adjusted for multiple potential confounding factors, including heart attack, vigorous work activity, education level, fractures, anti-osteoporotic, prednisone or Cortisone, HS C-Reactive Protein, smoking status, serum creatinine, serum uric acid, and alcohol consumption." (PMID 36050471, 2022). "Thus, CRP apheresis could be a valuable therapeutic option in the management of myocardial infarction patients, especially those with high CRP concentrations, defined as CRPgrad > 0.6." (PMID 36362673, 2022). "Notably, the correlation between the first troponin and the second CRP was stronger (r = 0.37, p < 0.01) and might reflect the slower rate of CRP increase compared to cardiac troponin following myocardial infarction." (PMID 35566579, 2022). "Research on systemic anti-inflammatory treatment of CVD first targeted C-reactive protein in rats with acute myocardial infarction (MI) to limit infarct size and cardiac dysfunction." (PMID 35354938, 2022).
myocardial infarction (continued). "In the present study, we found that several previously reported biomarkers were detected to be upregulated, including CRP, NGAL, and Cystatin C. CRP was first identified as a biomarker of inflammation and high concentrations are associated with mortality in patients with acute myocardial infarction." (PMID 35087594, 2022). "Similarly, 4000 mg/day of curcuminoid supplementation 3 days prior to and 5 days post coronary artery bypass grafting (CABG) was shown to reduce post-operative oxidative stress (malondialdehyde: MDA), inflammation (C-reactive protein: CRP) and myocardial infarction compared to a placebo control." (PMID 32503339, 2020). "Increased levels of CRP and interleukin-6 at hospital admission, in conjunction with increased BNP (brain natriuretic peptide) biomarker in convalescence, reflect the association between ventricular remodelling after myocardial infarction and impaired renal function." (PMID 32182690, 2020). "Recently, this hypothesis was confirmed in the Canakinumab Anti-inflammatory Thrombosis Outcome Study (CANTOS) trial, in which the IL-1β antagonism was able to reduce CVD in participants with previous myocardial infarction and high CRP levels, confirming the role of inflammation in CVD." (PMID 31513665, 2019). "Besides the potential mechanisms above, hypothyroidism can also lead to altered lipid metabolism, elevated C-reactive protein, and increased prevalence of aortic atherosclerosis, which can increase the prevalence of myocardial infarction and mortality in HF patients." (PMID 30947691, 2019). "CRP promotes the activation of local complement, leading to tissue damage; the serum CRP levels are increased in stable angina pectoris, unstable angina pectoris, and acute myocardial infarction, suggesting that they reflect severe injury in unstable angina pectoris plaques." (PMID 29409508, 2018). "Multivariable Cox-regression models were used to calculate hazard ratios (HR) with 95% confidence intervals (CI) for incident myocardial infarction (MI) and ischemic stroke across quintiles of hs-CRP and RDW." (PMID 31249941, 2018). "In the CANTOS trial, a multiyear study of >10,000 patients with previous myocardial infarction (MI) and high CRP levels, the anti-IL-1β antibody canakinumab provided dose-dependent reductions in CRP level and reduced the incidence of cardiovascular death." (PMID 30279971, 2018). "Moreover, another recent study involving anti-inflammatory therapy with Canakinumab, a monoclonal antibody targeting interleukin-1β, demonstrated a reduction in recurrent cardiovascular events in patients with previous myocardial infarction and raised CRP but at a cost of more fatal infection." (PMID 29376057, 2017). "The probable tissue damage by CRP following myocardial infarction mediated by complement is most likely due to binding of CRP to apoptotic cells and subsequent dissociation to monomeric CRP which may have proinflammatory qualities like classical complement activation by complement fixation." (PMID 24808639, 2014). "Similarly, increased plasma CRP is correlated to myocardial infarction, PD, and ischemic stroke." (PMID 21556377, 2011). "Risk of myocardial infarction and other thrombotic complications is typically higher during the winter months than during the summer, and in line with our study, fibrinogen (but not CRP) has been reported to vary by season." (PMID 20520739, 2010). "High levels of C-reactive protein increased the risk of heart failure by 160 percent compared to those with low levels, but they did not significantly raise the risk of a first stroke or heart attack." (PMID 17374166, 2007). "Moreover, modest anti-inflammatory therapy in the form of Aspirin was able to reduce the occurrence of myocardial infarction (MI) in those with the highest CRP levels." (PMID 40472800, 2025).
myocardial infarction (continued). "In parallel, C-reactive protein (CRP), a hepatic acute-phase reactant, provides robustprognostic information about systemic inflammation and vascular events, including myocardial infarction and ischemic stroke." (PMID 40978648, 2025). "Likewise, the Framingham Heart Study revealed that elevated baseline levels of TNF-α, IL-6, and CRP in individuals without a history of acute myocardial infarction (MI) are associated with a significantly increased long-term risk of developing HF, irrespective of MI occurrence." (PMID 40814000, 2025). "A novel fluorescence‐based aptasensor was developed for the measurement of CRP, tested in PBS solution and acute myocardial infarction patient serum." (PMID 41244339, 2025). "Relevant keywords and combinations such as “C-reactive protein,” “CRP,” “acute myocardial infarction,” “acute coronary syndromes,” “inflammation,” and “prognosis” were utilized." (PMID 40649166, 2025). "Thrombolysis in myocardial infarction (TIMI) scores were calculated, and serum C-reactive protein and albumin levels were measured within 24 hours of admission." (PMID 41018414, 2025). "Significant differences were found between myocardial infarction (p = 0.040), cardiovascular mortality (p = 0.006), and MACE (p = 0.009) in CHD patients with hs-CRP levels above and below 0.3 mg/dL." (PMID 38673472, 2024). "The presence of C-reactive protein (CRP) levels in serum and saliva was found to be directly correlated with acute myocardial infarction (AMI) patients, consistent with previous studies." (PMID 38433948, 2024). "In previous studies, the anti-inflammatory effects of chokeberry, expressed as a reduction in inflammatory markers such as C-reactive protein (CRP), IL-6, and VCAM-1, were observed in post-myocardial infarction patients taking chokeberry extract." (PMID 39859963, 2024). "After adjustment, only four variables, previous myocardial infarction, baseline TIMI flow, C-reactive protein and initial perfusion defect, correlated independently with a higher risk of CNR after primary PCI." (PMID 37685660, 2023). "CMRI, cardiac magnetic resonance imaging; CK, creatine phosphokinase; CRP, C-reactive protein; LV, left ventricular; TTE, transthoracic echocardiography; STe, ST-segment elevation; STEMI, ST-segment elevation myocardial infarction." (PMID 38292454, 2023). "There are many clinically relevant biomarkers identified for pathologies, such as troponins for acute myocardial infarction, prostate-specific antigen (PSA) for prostate cancer, or C-reactive protein (CRP) for inflammation or infection processes." (PMID 37998716, 2023). "A recent pilot study in humans (CAMI1) demonstrated a significant correlation between C-reactive protein (CRP) concentration or CRP increase during the 32 h after the onset of STEMI symptoms and myocardial infarct size (IS)." (PMID 37504550, 2023). "Accumulating evidence revealed that inflammatory biomarkers, such as NLR and CRP, have been reported to be correlated with adverse outcomes of CHD or acute myocardial infarction." (PMID 36088306, 2022). "In patients presenting with acute myocardial infarction and major cardiovascular events (MACE) at the one-year follow-up, hs-CRP, I-CAM, and MMP-9 were significantly increased and MMP-9 was the most powerful predictor for MACE." (PMID 36362423, 2022). "Furthermore, some polymorphisms in the CRP gene, which cause its overexpression, are likely to increase the risk of CAD and myocardial infarction (MI)." (PMID 36009459, 2022). "In contrast to the intoxicated group, the myocardial infarction model showed lower ALP, CK-MB, CRP, LDH, ALT, troponin, and AST levels (p > 0.005–0.000), as well as edema, necrosis, apoptosis, inflammatory cell enrolment, and necrosis." (PMID 35684321, 2022). "Studies have shown that inflammation indicators, such as C-reactive protein (CRP), systemic immune-inflammation index (SII), and neutrophil-lymphocyte ratio (NLR), are clearly related to myocardial infarction." (PMID 36627973, 2022).
myocardial infarction (continued). "In the multicenter, non-randomized, exploratory C-reactive protein (CRP) Apheresis in Myocardial Infarction (CAMI-1) study, CRP apheresis after ST-Elevation Myocardial Infarction (STEMI) significantly decreased blood CRP concentrations in humans." (PMID 36362673, 2022). "Reduced levels of C-reactive protein (CRP) and myeloperoxidase (MPO) in the rats started from day 4 after the induction of myocardial infarction." (PMID 35684249, 2022). "The recently proposed concept of CRP velocity can reflect the dynamic change and may better estimate the inflammatory process than CRP measured only once in a special situation (for example, differentiation between acute bacterial and viral infection and myocardial infarction." (PMID 36555941, 2022). "COPD—Chronic obstructive pulmonary disease, NAFLD—Non-alcoholic fatty liver disease, MI—Myocardial infarction, PGE2- Prostaglandins, MMP—Matrix metalloproteinase, IL—Interleukin, TNF-α—tumor necrosis factor-alpha, CRP—C-reactive protein." (PMID 36361416, 2022). "In this study, we analyzed dynamic changes in one well-established (CRP) and two more novel (PTX3, neprilysin) biomarkers in acute myocardial infarction." (PMID 35203485, 2022). "CK-MB, LDH, troponin, CRP, ALT, AST, ALP levels were shown to be lower in the myocardial infarction model, as were necrosis, oedema, and inflammatory cell recruitment in comparison to control." (PMID 34577135, 2021). "In comparison to the intoxicated group, the myocardial infarction model showed decreased troponin levels, CK-MB, LDH, ALT, ALP, AST, and CRP, as well as necrosis, apoptosis, oedema, and inflammatory cell enrollment." (PMID 35011482, 2021). "In addition, a previous publication showed that a poor clinical outcome after myocardial infarction (MI) can be predicted by increased serum CRP concentration." (PMID 34471467, 2021). "For the first time it is shown that specific CRP depletion in acute STEMI seems to result in clinical benefits and offers a new therapeutic approach as acute treatment of inflammation in myocardial infarction." (PMID 33778017, 2021). "The study investigates the levels of C reactive protein (CRP), interleukin 1β (IL-1β) and stromal-derived factor 1α (SDF-1α) at the time of acute myocardial infarction (AMI) and at 1 and 6 months afterwards, compared with a control group." (PMID 34180324, 2021). "In other clinical conditions such as myocardial infarction, PTX3 peaked in less than 12 h, whereas the CRP level peaked after 24 h after admission to the hospital." (PMID 32372340, 2020). "Lipid concentrations, blood glucose, C-reactive protein (CRP), interleukin 18 and adiponectin are also commonly used as markers for heart attacks and have been shown to be increased in the obese." (PMID 32471361, 2020). "Systemic Inflammation: Systemic inflammatory markers such as C-reactive protein (CRP), IL-6 etc. have shown direct correlation with specific indices of CVD such as carotid-intima media thickness, or MI (myocardial infarct size)." (PMID 33519515, 2020). "We explain the pathophysiological reasoning behind therapeutic CRP apheresis and summarize the broad span of indications in which its application could be beneficial with a focus on ischemic stroke as well as the results of this therapeutic approach after myocardial infarction." (PMID 32932587, 2020). "C reactive protein (CRP) is an inflammation marker of acute-phase response in infections (bacterial, viral, fungal), inflammatory diseases, necrosis (myocardial infarction, pancreatitis), trauma, and neoplasms." (PMID 31661804, 2019). "AMI: acute myocardial infarction; CRP: C-reactive protein; IL-6: interleukin-6; VCAM-1: vascular cell adhesion molecule 1; ICAM-1: intercellular adhesion molecule-1; ACEi: angiotensin-converting enzyme inhibitors; ARBs: angiotensin II receptor blockers." (PMID 31778438, 2019).